TNF (tumor necrosis factor)
Diseases named in the same sentence as TNF in open-access papers (continued):
Sharing a sentence is not in itself a finding about the gene and the disease.
cancer (continued). "In vivo studies assessing CYP activity in cancer patients have assessed concentrations of the pro-inflammatory mediators IL-1β, IL-6, IL-8, TNF-α, TGF, and the acute phase response protein, CRP15,20,25." (PMID 33707475, 2021). "TNF has an established role in inflammation and also plays a key role in inflammation-induced cancer." (PMID 33373873, 2021). "Activated TLR7 induces the production of different cytokines such as Interferon-α (IFN-α), Interleukin (IL)-12 and Tumor Necrosis Factor (TNF)-α, thus activating the immune system towards cancer cells." (PMID 34683910, 2021). "Cancer patients produce many inflammatory cytokines, such as tumor necrosis factor-alpha (TNF-α), proteolysis-inducing factor (PIF), interleukin-1 (IL-1), and interleukin-6 (IL-6)." (PMID 34724970, 2021). "Our group has previously shown that therapeutic index and anti-cancer activity of potent cytokines such as IL-2, IL-12 or TNF, can be improved by fusing them to the L19 antibody in various formats." (PMID 34576184, 2021). "Due to such cross talk, CTLs can initiate the antitumor effect through releasing IFN-γ and tumor necrosis factor α (TNF-α) to induce cytotoxicity in the cancer cells." (PMID 35003090, 2021). "Our study suggests that TNFα promotes cancer proliferation, progression, and nociception at least partially by activating Schwann cells." (PMID 33469141, 2021). "A number of immune cells (e.g., helper T cells and effector T cells) are recruited to distant tumors favoring effective cancer inhibition, thereby secreting proinflammatory cytokines such as TNF‐α, IFN‐γ, IL‐12P70 to inhibit cancer development and progression." (PMID 33643804, 2021). "TNF‐α, a cytokine naturally synthesized by the macrophages that directly leads to the death of cancer cells." (PMID 33849528, 2021). "It was found that TANs from early tumors showed more cytotoxic properties toward cancer cells and produced higher levels of TNF-alpha, NO, and H2O2 showing antitumor N1 features." (PMID 35008550, 2021). "Cancer cells and CAFs release similar inflammatory cytokines such as IL-6 and TNF-α, and it is considered reasonable that CAFs are induced by Ca.-CM and CAF-CM." (PMID 33659044, 2021). "On the other hand, increasing evidence has been accumulating about the positive impact of TNFα-blocking strategies in cancer treatment." (PMID 33540543, 2021). "Myotubes treated with TNF-α (formerly termed cachectin) have also been used to model cancer cachexia." (PMID 34038481, 2021). "The functions of TNFα include regulating the EMT transition in many cancers, These pathways are interrelated and are elevated via subsets of MHC-I+ EVs in a CD47-dependent manner." (PMID 34829933, 2021). "TNF and LT were discovered as cytotoxic substances and are considered to be promising agents for cancer therapy." (PMID 33917839, 2021). "Macrophages release TNF-α which leads to the apoptosis of cancer cells as shown in colorectal cancer metastasis in the liver." (PMID 33800554, 2021). "More recently, researchers have begun to study the therapeutic potential of TNFα and IL-1β inhibition in cancer." (PMID 33776573, 2021). "These miRNAs were related to mitogen-activated protein kinase (MAPK) signaling, apoptosis, and tumor necrosis factor (TNF) pathways, all regulators of cancer development, progression, and immune escape." (PMID 35223454, 2021). "These trials highlighted the need to further explore the use of TNFα-blocking agents in combination with radiotherapy and chemotherapy for advanced cancer treatment, yet scarce progress has been made in this direction." (PMID 33540543, 2021). "Some factors released in the bone microenvironemnt by cancer and stromal cells, including interleukin‐6 (IL‐6) and tumour necrosis factor α (TNF‐α), are able to induce osteoclast differentiation in vitro independently of RANK activation." (PMID 32955748, 2021).
cancer (continued). "C26 adenocarcinoma led to significant cancer cachexia accompanied by muscle degeneration with disturbed muscle regeneration, high TNF-α and IL-6 levels, MAPK activation leading to increased atrogin-1/MuRF-1 levels, and lipolysis." (PMID 34262449, 2021). "On the other hand, it has been reported that the increase in IL-1β favors the production of angiogenic factors, such as TNF-α (tumor necrosis factor), which is responsible for increasing the content of malignant tumors in oral tissues." (PMID 34829898, 2021). "M1 macrophages kill invading pathogens and cancer cells by producing pro-inflammatory cytokines, such as IL-1β, IL-6, and TNFα." (PMID 33406733, 2021). "Previous studies from several groups reported that miR-145, miR-15a, miR-29a, miR-181A, miR-19a, miR-130a, miR-21, miR-765 are regulated by TNF-α in several cancers produced by both cancer cells and TME-related immune cells." (PMID 33986746, 2021). "Meanwhile, DDX39 was found to be correlated with hallmarks (such as MYC, G2M, E2F, TGF-β and TNF-α) that participate in cancer activation and cycle acceleration." (PMID 34421357, 2021). "The CXCL1 is often cosecreted with inflammatory cytokines such as IL-1, IL-6, and TNF-α by infiltrating macrophage or cancer cells." (PMID 34803728, 2021). "This review summarizes findings regarding the role of TNF and LTα in transplantable and chemically induced mouse cancer models and discusses some unresolved controversies." (PMID 33917839, 2021). "Previous studies have shown that TNF-α enhances antitumor effects when used in combination with other cancer therapeutics and cytokines, including adriamycin, actinomycin D, and IFN-γ." (PMID 33668827, 2021). "Due to its plethora of functions through its two receptors, TNF-α is responsible for divergent actions in the context of cancer." (PMID 34712661, 2021). "Meanwhile, TNF-α induces the release of chemokine (such as IL-8) and activates NF-kB transcription factors, which play an essential role in cancer progression." (PMID 34287243, 2021). "This fact makes the process of apoptosis induction in cancer cells a little clearer by inhibiting the activity of tumor necrosis factor α (TNF-α) with the participation of biogenic amine." (PMID 35053172, 2021). "In cancer, TNF-α secreted by activated T-cells increases the proliferation of HSPCs and induces emergency myelopoiesis in the bone marrow." (PMID 33669537, 2021). "In the current study, we focused on the cancer signaling pathways, including TNF-α-induced NF-κB and IGF-1-induced PI3K/AKT and AMPK pathways." (PMID 34361052, 2021). "In the clotting assay, recalcified human plasma was incubated with cancer cells in the absence or presence of TNF-α." (PMID 33633307, 2021). "The exposure of mesenchymal stem cells to the proinflammatory cytokines, tumor necrosis factor-alpha (TNF-α) and interleukin-1 beta (IL-1β) can lead to the development of the cancer-associated fibroblast (CAF) phenotype." (PMID 34638283, 2021). "Cancer- or TNFα-activated Schwann cells release pro-nociceptive mediators such as TNFα and nerve growth factor (NGF)." (PMID 33469141, 2021). "Although TNF apoptosis-inducing ligands have been designed as cancer therapies and analyzed in preclinical studies showing promising results, only a few have reached clinical trials." (PMID 33801589, 2021). "We provide clinical and preclinical evidence that TNFα promotes cancer progression and pain, at least in part through Schwann cell activation." (PMID 33469141, 2021). "As previously reported, the malignant tumors incite a systemic inflammatory response, which often triggers the release of inflammatory cytokines and chemokines, such as tumor necrosis factor and IL-1 and IL-6." (PMID 34917503, 2021). "Curcumin, a polyphenol, suppressed tumor necrosis factor (TNF) when incorporated into cancer cells in various cells lines through interaction with various stimuli." (PMID 34641312, 2021).
cancer (continued). "The main molecular players in the inflammation-to-cancer axis are proinflammatory mediators such as TNF-α and IL-6." (PMID 34447314, 2021). "In vitro studies revealed that the expression of ICs was closely linked with aggressive CCA subpopulations, such as cancer stem cells and cells undergoing TGF-β and TNF-α-mediated epithelial-to-mesenchymal transition." (PMID 34069452, 2021). "Increased levels of inflammatory cytokines, such as IL-6, IL-8, and TNF-α, are known to promote migration, invasion and metastasis of various types of cancer and inhibition of these pathways represent a promising approach in cancer treatment." (PMID 33430013, 2021). "The complexity of these findings tempered the original enthusiasm for TNFα as a breakthrough molecule for cancer therapy." (PMID 34445397, 2021). "M1-Mφs produce significant amounts of proinflammatory cytokines (e.g., interleukin (IL)-1β, IL-6, IL-12, IL-23, and tumor necrosis factor alpha (TNF-α)) and retain robust and antitumor capabilities in certain stages of cancer development and progression." (PMID 34281268, 2021). "Among the pro-inflammatory mediators, tumor necrosis factor alpha (TNFα) has been identified as an important player in cancer progression and metastasis." (PMID 33540543, 2021). "It is also possible that already elevated levels of cytokines such as IL-6 and TNF-α in cancer patients offer protection in the initial stages of SARS-CoV-2 infection, offering a certain degree of immune-preparedness." (PMID 34830872, 2021). "Inhibition of NF-κB has been shown to impede the transcription of CDH2, SLUG, TWIST1 and SNAIL in some cancer cell lines and NF-κB activation by TNF or expression of constitutively active IKK2 can induce an EMT-phenotype." (PMID 34572737, 2021). "Additional studies are warranted to evaluate the causal relationship between the baseline serum levels of specific TNF cytokines and the adverse cardiac events in cancer patients receiving anthracycline treatment." (PMID 33719006, 2021). "CAR-T cells lead to cancer cell death mainly via the secretion of cytotoxic granules containing granzymes and perforin, and the release of cytokines (i.e., IFNγ and tumor necrosis factor (TNF))." (PMID 35008250, 2021). "As chronic inflammation plays an important role in hepatocellular carcinogenesis, the proinflammatory cytokine TNFα, which is mainly secreted by macrophages, is involved in cancer cell proliferation." (PMID 34445462, 2021). "The most enriched KEGG pathways included extracellular matrix receptor interaction, proteoglycans in cancer, complement and coagulation cascade, tumor necrosis factor signaling pathway, and cell death among others." (PMID 33314711, 2021). "On the other hand, consistent with our observations in NMSC patients, the increased serum levels of TNF-α has been described in various independent cancer types." (PMID 33461943, 2021). "As reported, the TNF is a cytokine and played an important role in inflammatory reaction, immune response, and cancer-related pathways." (PMID 35047409, 2021). "Acute stimulation of T lymphocytes leads them to differentiate into Th1 cells and secrete INFγ, TNFα and IL-2 to synergistically inhibit cancer development with CD8+ T cells." (PMID 34034721, 2021). "Similar to TGF-β, tumor necrosis factor-α (TNF-α) is a crucial inflammatory cytokine involved in malignant transformation of human cancers." (PMID 33668218, 2021). "Among the significantly enriched pathways, the cGMP-PKG signaling pathway and TNF signaling pathway played indispensable roles in the biological processes of human cancers." (PMID 34888137, 2021). "TNFα, producing by the activation of NF-κB signaling, is one of the important stimuli of NF-κB signaling which regulates inflammation, innate immune, cancers, and neurodegenerative diseases." (PMID 34535633, 2021). "TNF-α is a pleiotropic cytokine and acts as pro- or anti-tumorigenic depending on the type and stage of specific cancer." (PMID 33926547, 2021).
cancer (continued). "The final effect of TNFα is dependent on the type of malignant cells, with the potential to arrest cancer progression." (PMID 33957885, 2021). "This review focuses on the diverse molecular mechanisms that place TNFα as a source of resistance to immunotherapy such as monoclonal antibodies against cancer cells or immune checkpoints and adoptive cell therapy." (PMID 33540543, 2021). "have found that tumor necrosis factor α+ cycloheximide and navitoclax-induced cancer cell pyroptosis through a BAK/BAX-caspase-3-GSDME signaling pathway." (PMID 34484243, 2021). "NKT cells also cause liver infiltration by M1 macrophages and act against cancer by producing and secreting TNF-α." (PMID 33800554, 2021). "The first logistic regression model including IL-6, IL-8, and TNFα showed that elevated IL-6 significantly increased the likelihood of having a diagnosis of cancer (p = 0.0040, odds ratio 3.991)." (PMID 35048057, 2021). "TNFα was found to have a role in cancer promotion and progression, including cellular transformation, proliferation, invasion and metastasis." (PMID 33799622, 2021). "In view of the powerful roles of CAFs in regulating cancer progression, we explored the possibility that CAFs obtained following persistent stimulation of MSCs by TNFα + IL-1β undergo alterations in the expression of cancer-related genes." (PMID 33806906, 2021). "TNF-induced apoptosis was observed in cell lines of multiple cancer types under normoxia, whereas the same treatment induced necrotic cell death under hypoxia." (PMID 33406603, 2021). "The expression profile of inflammation- and cancer-related genes (IL-1β, IL-8, TNF-α, IFN-γ, IL-6, NF-κB, and IL-13) were measured using qPCR." (PMID 37901256, 2021). "Further RNA sequencing analyses showed that massive signaling pathways, particularly the TNF signaling pathway and nuclear factor-kappa B (NF-κB) signaling pathway, were affected in siRNA-treated cancer cells." (PMID 34789165, 2021). "In this review, we discuss evidence for an oncogenic role of TNF in cancer with a focus on non-small cell lung cancer (NSCLC)." (PMID 33373873, 2021). "Many cancer- and inflammation-related transcription factors, as NF-κB, HIF1α, TGFβ, TNFα are involved in the transcriptional regulation of CLU during cancer progression." (PMID 34360868, 2021). "PPI network analysis of the three SOX proteins revealed their functional protein partners to be categorized in several cancer-related pathways, including the TNF/β-catenin and WNT signaling pathways." (PMID 34442467, 2021). "Five of these signatures, including IFNα, IFNγ, STAT3, TGFβ and TNFα pathway signatures, are cancer immunity-related." (PMID 33767579, 2021). "TAM-derived TNF-α also enhances cancer cell migration toward ECs, endothelial permeability, and cancer cell intravasation in 3D fibrosarcoma and breast cancer models." (PMID 33783686, 2021). "The serum levels and muscle tissue levels of IL-1β, tumor necrosis factor-α (TNF-α), and especially IL-6 are significantly increased in patients with cancer cachexia, which aggravates the condition and negatively affects patients’ prognosis." (PMID 34552592, 2021). "They fight against bacterial infections, angiogenesis, and cancer cells, and secrete pro-inflammatory cytokines such as interleukin-1 (IL-1) and tumor necrosis factor (TNF)." (PMID 34281293, 2021). "“TNF signaling pathway” and “Transcriptional misregulation in cancer” also played important roles in regulation of cell cycle, proliferation and apoptosis." (PMID 33479397, 2021). "Similar analysis including IL-1β, Rantes/CCL5, MCP1, GMCSF, TNFα, and IL-6 showed similar results with elevated IL-6 increasing the probability of having a cancer diagnosis (p < 0.0046)." (PMID 35048057, 2021). "Although TNF-α was used as a treatment for cancer at first, it is now considered to promote cancer by developing blood vessels, activating oncogene, and causing DNA damage." (PMID 34422050, 2021).
cancer (continued). "Tumor necrosis factor (TNF) is a cytokine that plays a central role in inflammation, the immune response, and in cancer." (PMID 33373873, 2021). "Tumor necrosis factor (TNF)-related apoptosis-inducing ligand (TRAIL) mediated apoptosis is another mechanism which immune cells use to kill cancer cells." (PMID 34207884, 2021). "Previously, dexmedetomidine was found to significantly suppress TNF- α and IL-6 levels in patients undergoing laparoscopic ovarian resection for cancer." (PMID 34692497, 2021). "Fourth, despite RIP1 is essential for cellular response to TNF-α/SM treatment, it is completely dispensable in the response to anti-cancer drugs." (PMID 33800107, 2021). "Further virological and cancer-registry studies are needed in this population to analyse the suggested association between P. falciparum Malaria, EBV and TNF-α in causing chronic or malignant EBV-related disease." (PMID 34962938, 2021). "TNF-α plays a crucial role in cancer initiation and progression by enhancing cancer cell proliferation, survival, and migration." (PMID 33816268, 2021). "As regulator of cytotoxic, pro-, and anti-inflammatory functions, it is evident that TNFα can play a critical role in the development of chronic inflammatory diseases as well as cancer." (PMID 34445397, 2021). "The roles of TNF-α in different transcription factors, cytokines, and signaling pathways by cancer type." (PMID 33986746, 2021). "Evidence shows that despite the several side effects of using TNF-α in cancer therapy, beneficial therapeutic effects have been observed in some cancers such as sarcoma and melanoma." (PMID 34868907, 2021). "KEGG pathway enrichment analysis revealed that MRGs primarily participated in the TNF and NF-kappa B signaling pathways, two signaling pathways known drive metastasis in other cancers." (PMID 34368151, 2021). "TNF can induce cell death in cancer cells and has been used as a treatment in certain types of cancer." (PMID 33373873, 2021). "GO and KEGG pathway analyses indicated that hsa-miR-650 participates in pathways in cancer and TNF signaling." (PMID 34804121, 2021). "Clostridium acetobutyicum was one of the first to be investigated for its anti-cancer activity, as studies showed the ability to effectively engineer C. acetobutyicum to secrete mouse TNF-α." (PMID 34960243, 2021). "TNFα recruits neutrophils to the environment that promotes cancer invadopodia formation and invasiveness." (PMID 33469141, 2021). "Other cytokines like IL-6, IL-19, IL-20, TGF-α, TNF-α, and IL-23 are also known to promote cancer progression." (PMID 34681026, 2021). "Lack of NR4A1 in TME macrophages promotes inflammatory cytokine TNF-α production, which stimulates cancer cells to undergo EMT and promotes invasive properties." (PMID 33634114, 2021). "TNF-α is regarded as a potent mutagen that promotes cellular transformation through the induction of reactive oxygen species (ROS), which can affect cancer cell migration/invasion and thereby promote cancer initiation and progression." (PMID 33816268, 2021). "It was revealed that transcripts in gastric cancer cells were most enriched in the TNF signaling pathway, as compared with several other cancer‐related pathways, as shown by the KEGG pathway analysis in MGC803 cells." (PMID 33731118, 2021). "Here, we review the mechanisms of TNF/LTα involvement in cancer promotion and suppression as studied in mouse models." (PMID 33917839, 2021). "By activating the mitogen-activated protein kinases (MAPK) pathway or other signaling to induce EMT, TNF-α promotes the invasive and metastasis capacity of cancer cells." (PMID 33668218, 2021). "Cancer biology and its proliferation, migration, angiogenesis, survival, and invasion it is promoted by TNF." (PMID 34063545, 2021). "Mean total pain scores reported by patients correlated positively with the percentage change of TNFα concentration between the cancer and the matched contralateral normal tissues (r = 0.7, P < 0.05)." (PMID 33469141, 2021).